PDK1 (pyruvate dehydrogenase kinase 1)
Description:
Kinase that plays a key role in regulation of glucose and fatty acid metabolism and homeostasis via phosphorylation of the pyruvate dehydrogenase subunits PDHA1 and PDHA2. This inhibits pyruvate dehydrogenase activity, and thereby regulates metabolite flux through the tricarboxylic acid cycle, down-regulates aerobic respiration and inhibits the formation of acetyl-coenzyme A from pyruvate. Plays an important role in cellular responses to hypoxia and is important for cell proliferation under hypoxia.
Tractability: Small molecule: an approved drug acts on it; a structure with a bound ligand is known; a high-quality ligand is known; it has a binding pocket of medium quality; it belongs to a druggable protein family. PROTAC: it is named in the literature on targeted protein degradation; ubiquitination databases record sites on it; its protein half-life has been measured; a small molecule that binds it is known.
Target class: Kinase; Enzyme; Atypical protein kinase PDHK subfamily; Atypical protein kinase group; Protein Kinase
Chemical probes: GSK2334470 (high quality), PD134192, PD134194
Safety:
Unwanted effects reported when the protein is acted on. In parentheses: how it was acted on, where the effect was seen, and who reports it.
Abnormal myelination (inhibition; source: Brennan et al. (2024))
hypoglycaemia (inhibition; metabolic; source: Brennan et al. (2024))
ketoacidosis (inhibition; source: Brennan et al. (2024))
mutagenic effect (inhibition; source: Brennan et al. (2024))
nervous system disorder (inhibition; central nervous system; source: Brennan et al. (2024))
peripheral neuropathy (inhibition; source: Brennan et al. (2024))
seizure (inhibition; central nervous system; source: Brennan et al. (2024))
testicular disorder (inhibition; reproductive; source: Brennan et al. (2024))
Gene: Protein-coding gene on chromosome 2 (172,555,373 to 172,608,669, forward strand). Ensembl gene ENSG00000152256.
Subcellular location: Mitochondrion matrix
Pathways (Reactome):
Metabolism: Regulation of pyruvate dehydrogenase (PDH) complex
Metabolism of proteins: Mitochondrial protein degradation
Signal Transduction: Signaling by Retinoic Acid
Gene Ontology:
Molecular function: protein binding; protein kinase activity; pyruvate dehydrogenase (acetyl-transferring) kinase activity
Biological process: cell population proliferation; hypoxia-inducible factor-1alpha signaling pathway; intrinsic apoptotic signaling pathway in response to oxidative stress; phosphatidylinositol 3-kinase/protein kinase B signal transduction; regulation of glucose metabolic process; glucose metabolic process; regulation of pyruvate decarboxylation to acetyl-CoA; cellular response to stress
Cellular component: mitochondrial matrix; mitochondrion; plasma membrane; pyruvate dehydrogenase complex
Genetic constraint (gnomAD): Loss-of-function variants: 14 observed, 17.25 expected, observed/expected ratio (o/e) 0.81, 90% interval 0.54 to 1.27. The upper end of that interval is the gene's LOEUF score, 1.27, which puts it in group 5 of 6, group 1 being the genes least tolerant of losing a copy. Missense variants: 288 observed, 258.5 expected, observed/expected ratio (o/e) 1.11, 90% interval 1.01 to 1.23. Synonymous variants: 118 observed, 95.87 expected, observed/expected ratio (o/e) 1.23, 90% interval 1.06 to 1.43.
Homologues: Orthologues: chimpanzee PDK1 (99% identical), macaque PDK1 (99% identical), pig PDK1 (96% identical), guinea pig PDK1 (95% identical), dog PDK1 (94% identical), rat Pdk1 (93% identical), mouse Pdk1 (92% identical), tropical clawed frog pdk1 (77% identical), zebrafish pdk1 (72% identical), Drosophila melanogaster Pdk (52% identical), Caenorhabditis elegans pdhk-2 (45% identical). Paralogues in human: PDK2 (64% identical), PDK3 (63% identical), PDK4 (61% identical), BCKDK (30% identical).
Diseases named in the same sentence as PDK1 in open-access papers:
PDK1 is named in the same sentence as 228 diseases in open-access papers, as found by Europe PMC text mining. Sharing a sentence is not in itself a finding about the gene and the disease. The quoted sentences say what the papers report.
breast cancer (170 papers, 2005 to 2025). A primary or metastatic malignant neoplasm involving the breast. "We found that compared to cells with wild-type PIK3CA (n = 13), PIK3CA-mutant breast cancer cell lines (n = 7) displayed increased dependency on PDK1 and were more susceptible to PDK1 knock-out for their proliferative capacity." (PMID 38273040, 2024). "Specific activation of PDK1 in BRCA2 mutation carriers is interesting as this kinase has recently been shown to confer resistance to CDK4/6 inhibitors in ER+ breast cancer cell lines, and inhibitors targeting this kinase are under development." (PMID 38059556, 2024). "It interacts with PDK1 (phosphoinositide-dependent kinase 1) to cause Akt phosphorylation at breast cancer to play a role." (PMID 33859949, 2021). "PDK1 is required for the activation of AKT, and increased PDK1 expression in breast cancer is associated with ERBB2 amplification and PIK3CA mutations." (PMID 33933113, 2021). "PDK1 mRNA and protein are overexpressed in the majority of breast cancers and 21% of these tumors have five or more copies of the gene encoding PDK1, PDPK1." (PMID 32210163, 2020). "Evidence includes a study demonstrating that PDK1-mediated SGK3 activation was critical for anchorage-independent growth in a subset of PIK3CA (the gene encoding for p110α) mutant breast cancer cell lines with minimal Akt activation." (PMID 31088502, 2019). "Pyruvate dehydrogenase kinase 1 (PDK1), a key enzyme implicated in metabolic reprogramming of tumors, is induced in several tumors including glioblastoma, breast cancer and melanoma." (PMID 28505181, 2017). "Previous research has been found that PDK1 is associated with various types of cancers including melanoma, breast cancer, lung cancer, stomach cancer, prostate cancer, ovarian cancer, and pancreatic cancer." (PMID 26593251, 2016). "Expression of PDK1 induces anchorage-independent growth in vitro, a hallmark of cellular transformation, and injecting PDK1 cell into nude mice induces homologous, poorly differentiated cells, leading to the formation of breast cancer." (PMID 26318166, 2015). "We used immunohistochemical analysis to determine PDK1 expression in 241 tumors from patients with breast cancer in which we had previously analyzed PIK3CA mutation status." (PMID 24739482, 2014). "The fact that some cases without PIK3CA mutations had a moderate or high expression of PDK1 suggests that PDK1 can be independently activated in breast cancer and not only as part of the PIK3CA pathway." (PMID 24739482, 2014). "We have previously linked the tumorigenic phenotype of Comma/PDK1 cells to the disappearance of another breast cancer tumor suppressor, caveolin-1." (PMID 16551362, 2006). "This was the first report illustrating PDK-1 phosphorylation was frequently elevated and was significantly associated with the invasiveness of breast carcinoma (P<0.05)." (PMID 16288304, 2005). "PDK1 overexpression causes tumor development and adriamycin resistance in breast cancer, and thus, the HDAC2/EZH2/miR-148a/PDK1 axis may represent a potentially promising therapeutic target." (PMID 38891056, 2024). "PDK1, is implicated in various cancers, including breast cancer." (PMID 35164019, 2022). "As a result, PDK1 is implicated in the resistance of ER+ breast cancer cells to CDK4/6 inhibitors." (PMID 34830174, 2021). "Moreover, spheroids exhibited much higher protein expression of PDK1, which was associated with higher levels of stemness-related factors in three breast cancer cells." (PMID 29106390, 2018). "Recently, it has been shown that PDK1 regulates anchorage-independent growth, resistance to several anticancer drugs, and tumor formation in breast cancer cells–not only in tumors harboring PIK3CA mutations, but also in the absence of these genetic alterations." (PMID 24739482, 2014). "Lastly, the co-association of PDK1 and PPARδ noted in mammary tumors may also have enhanced resistance of the receptor to ubiquitination and degradation." (PMID 21297860, 2011).
breast cancer (continued). "The FB23-everolimus combination synergistically inhibits pancreatic neuroendocrine tumors 15; similarly, the combination of FB23 and BX-912 targets FTO and the PDK1-AKT pathway to suppress breast cancer." (PMID 41281757, 2025). "Our finding of the enrichment of H3K36me3 mark near the HREs of TWIST1 and SNAIL1 promoters is in interesting parallel to the increase of H3K36me3 mark at the HRE region of PDK1 gene in breast cancer cell line SUM159 upon hypoxia treatment." (PMID 40764968, 2025). "Silencing EMC2 significantly weaken the proliferation/metastasis potential of breast cancer in vitro and in vivo, but made tumor cell sensitive to PDK1/AKT inhibition." (PMID 40303285, 2025). "Drug sensitivity experiments revealed that EMC2 overexpression sensitizes breast cancer cells to PDK1 or AKT inhibition both in vitro and in vivo, whereas EMC2 silencing has the opposite effect." (PMID 40303285, 2025). "In summary, our study provides strong evidence for the mechanism of EMC2 in the development and progression of breast cancer, and highlights its significant potential as a target for PDK1/AKT inhibition." (PMID 40303285, 2025). "PDK1 expression levels were significantly increased in lung, colon, liver, and breast cancer tissues compared with those in normal tissues." (PMID 42004224, 2025). "Among these, p21 and PDK1 are related to cancer cell proliferation and colony formation ability in breast cancer and are regulated via proteasomal degradation by RNF126." (PMID 41465608, 2025). "In this study, we demonstrated that EMC2 was aberrantly upregulated in breast cancer tissues, significantly enhanced the proliferation and metastasis potential of tumor cells, and increased the sensitivity of tumor cells to PDK1/AKT inhibition." (PMID 40303285, 2025). "ENO1 subsequently promotes breast cancer progression by stabilizing the expression of the downstream transcription factor B-MYB, which ultimately activates the PDK1/AKT/mTOR signaling pathway thereby promoting breast cancer progression." (PMID 40303285, 2025). "Remarkably, proteins prominently expressed in NmFMC compared with other groups, such as F13A1, CENPF, INSR, SCAF1 and PDK1, have been implicated in human breast cancer, further supporting the potential use of FMC as a model for studying human breast cancer." (PMID 38951817, 2024). "PDK1, a key regulator of MR, is elevated in liver metastasis of breast cancer patients and can promote tumor cell proliferation and migration by enhancing the Warburg effect." (PMID 39588377, 2024). "We found that PDK1 was highly expressed in breast cancer tissues, and PDK1 knockdown reduced the proliferation, migration, and tumorigenicity of breast cancer cells and inhibited the HIF-1α (hypoxia-inducible factor 1α) pathway." (PMID 38560503, 2024). "We found that high expression of PDK1 in breast cancer cells significantly promoted cell proliferation and migration and inhibited cell apoptosis." (PMID 38560503, 2024). "We identified a novel role and regulatory mechanism of the PDK1/HIF-1α positive feedback loop in breast cancer, which provides a promising strategy for breast cancer treatment." (PMID 38560503, 2024). "After PDK1 down-regulation, the proliferation, migration, and anti-apoptotic properties of breast cancer cells were markedly inhibited." (PMID 38560503, 2024). "PDK1 is highly expressed in breast cancer tissues and its knockdown results in impaired growth and motility of breast cancer cells, in addition to inhibiting HIF-1α signalling." (PMID 39282472, 2024). "Meanwhile, PDK1 knockdown reduced the proliferation, migration, and tumorigenicity of breast cancer cells and inhibited the HIF-1α signaling pathway." (PMID 39199957, 2024). "Here, JMJD2C removes H3K9me3 marks and enhances the binding of HIF-1α leading to enhanced expression of key genes required for breast cancer progression (PDK1) and metastasis to the lung (LOXL2 and L1CAM)." (PMID 39282472, 2024).
breast cancer (continued). "CRY1-mediated decrease of Pdk1 expression can also be observed in a breast cancer cell line MDA-MB-231, whose glycolysis is associated with Pdk1 expression." (PMID 38199564, 2024). "In vitro and in vivo studies on breast cancer have shown that PDK1 increases cells’ proliferation, migration, and invasion, as well as tumor growth and metastasis." (PMID 39199957, 2024). "3-Phosphoinositide-dependent kinase 1 (PDK1) is also a potential target since myeloid-selective knockout of PDK1 alters the phenotype of TAMs, enhances IFNγ expression in NK cells, and suppresses tumour growth in a mouse breast cancer model." (PMID 37313600, 2023). "A small number of recent studies have linked aspirin’s anti-cancer effects to metabolism; aspirin has been found to inhibit glucose metabolism through the regulation of PDK1 in breast cancer cells and through the regulation of GLUT1 in hepatoma cells." (PMID 37858256, 2023). "H19 sponges microRNA let-7 to release HIF1-α (Hypoxia-inducible factor 1α), which in turn activates a cascade of target genes, among which the glycolytic enzyme PDK1 (Phosphoinositide-dependent kinase-1) plays a master role in breast cancer stem cells." (PMID 36768150, 2023). "Ablation of PDK1 prevented H19-mediated glycolysis in breast cancer stem cells, and H19 knockdown reduced PDK1 expression through the let-7/HIF-1 axis in hypoxia." (PMID 37821504, 2023). "PDK1 was overexpressed in osteosarcoma, multiple myeloma, acute myelogenous leukemia, and breast cancer." (PMID 37937197, 2023). "PDK1 is required for breast cancer cells to adapt to hypoxia and a nutrient-deprived microenvironment." (PMID 37444501, 2023). "We revealed the roles of ATP-HIF-1α and the HIF-1 target genes ADM and PDK1 in promoting breast cancer chemoresistance." (PMID 35236823, 2022). "The PI3K-PDK1 signaling pathway has been implicated in mediating resistance to CDK4/6 inhibitors, with ribociclib-resistant breast cancer cell lines demonstrating an increase in PDK1 levels following drug exposure, resulting in activation of the AKT pathway." (PMID 35053461, 2022). "We hope the information provided on clinical trials of PDK1-targeted therapies will benefit researchers and clinicians in the breast cancer field." (PMID 35159078, 2022). "In this study, primary in vitro studies showed the upregulation of phosphorylated and total PDK1 protein levels in ribociclib-resistant ER+ breast cancer cells, generated by chronic drug exposure." (PMID 35892870, 2022). "In the present study, we demonstrated that PDK1 is a new direct target of miR-148a in mediating the development of breast cancer and Adriamycin resistance." (PMID 35892859, 2022). "The elevated levels of PPARβ/δ were accompanied by increased activation of 3-phosphoinositide-dependent protein kinase 1 (PDK1), revealing that PPARβ/δ plays a role in promoting breast cancer development through the PDK1 signaling pathway." (PMID 36611922, 2022). "We carried out Transwell assays to evaluate the migration ability of miR-148a and PDK1 in the breast cancer cells, and showed that PDK1 counteracted the inhibitory effect of miR-148a on cell migration ability." (PMID 35892859, 2022). "The effects of PDK1 and miR-148a in breast cancer were investigated by immunofluorescence (IF) assay, Transwell assay and flow cytometry assay." (PMID 35892859, 2022). "Epigenetic modification and miR-148a have important regulatory roles on PDK1; in this way, how these two factors control the specific mechanism of the abnormal expression of PDK1 in breast cancer needs to be further explored." (PMID 35892859, 2022). "In our study, we found that PDK1 expression levels were significantly higher in breast cancer tissues and cell lines." (PMID 35892859, 2022). "At the post-transcriptional level, PDK1 was a new direct target of miR-148a and was upregulated in breast cancer cells due to miR-148a suppression." (PMID 35892859, 2022).
breast cancer (continued). "To study the role of PDK1 in breast cancer, we showed that PDK1 levels were significantly higher in breast cancer tissues than normal tissues using the GSE22820 breast cancer dataset for normal (n = 10) and breast cancer tissues (n = 176)." (PMID 35892859, 2022). "An independent study in breast cancer also showed that hypoxia promoted breast CSC properties through pyruvate dehydrogenase kinase 1 (PDK1)." (PMID 36358763, 2022). "In our study, we demonstrated that miR-148a increased breast cancer cells’ sensitivity to Adriamycin through targeting PDK1." (PMID 35892859, 2022). "HIF-1α regulates PDK1 mediated glycolytic metabolism in liver-metastatic breast cancer cells, revealing a pivotal role in the progression of liver metastasis." (PMID 36076967, 2022). "Abnormalities regarding epigenetics modification and pyruvate dehydrogenase kinase 1 (PDK1)-induced unusual metabolism contribute to breast cancer progression and chemotherapy resistance." (PMID 35892859, 2022). "Exogenous expression of PDK1 enables PDK1 to silence breast cancer cells, allowing them to revert to a mesenchymal state." (PMID 35736645, 2022). "The hypoxia-regulated lncRNA H19 and PDK1 (pyruvate dehydrogenase kinase 1) expression exhibits strong correlations in primary breast carcinomas, and they promote reprogramming of cancer stem cells." (PMID 35368654, 2022). "Given that 3-phosphoinositide-dependent kinase 1 (PDK1) plays a crucial role in the malignant biological behaviors of a wide range of cancers, we review the influence of PDK1 in breast cancer (BC)." (PMID 35159078, 2022). "A high throughput in vitro siRNA screen in breast cancer cells identified that PDK1 knockdown increases the sensitivity of cells to CDK4/6 inhibition." (PMID 34830174, 2021). "The anti-inflammatory drug aspirin inhibits the level of glycolysis by inhibiting the expression of PDK1 and reducing the glucose uptake, lactic acid production and ATP levels of tumor cells, thereby killing breast cancer stem cells." (PMID 33739396, 2021). "For instance, as a core regulator of glycolysis, PDK1 has been found to reprogram stem cells under hypoxia circumstances in breast cancer." (PMID 34408553, 2021). "It has been shown that pyruvate dehydrogenase kinase 1 (PDK1) is abundant in breast cancer stem cells." (PMID 34926688, 2021). "In detail, ROR2 overexpression promotes PI3K activation and AKT phosphorylation, followed by the downregulation of p21 and upregulation of cyclin D1 and PDK1, resulting in increased proliferation and survival of breast cancer cells." (PMID 34440262, 2021). "Treatment with GW501516 increased the number of mammary tumors and reduced survival, which was even more pronounced in animals with PDK1 overexpression." (PMID 32375405, 2020). "Liver metastatic breast cancer cells are recognized to depend on the HIF-1/PDK1 axis for their metabolic reprogramming to accelerate their efficient colonization and proliferation in the liver." (PMID 33489906, 2020). "It was reported that PDK1 downregulation in metastatic breast cancer greatly alters the tumor cell capability to utilize glucose as an energy source for the mitochondria under hypoxic or limited glucose conditions." (PMID 32039832, 2020). "It is important to note that in this study on Chinese breast cancer patients the frequency of PIK3R1, AKT1, AKT2, AKT3, and PDK1 mutations was higher than that observed in the TCGA data set." (PMID 32210163, 2020). "For example, HIF1a leads to the upregulation of PDK1, which accelerates glycolysis and plays a critical role in promoting stem-cell traits of breast cancer stem cells." (PMID 32642002, 2020). "PDPK1 amplification and PDK1 over-expression are observed in several human cancers, including breast cancer." (PMID 32630372, 2020). "Previous studies have found that FKBP4 can interact with PI3K in breast cancer and activate Akt through PDK1 and mTORC2, thereby activating the Akt/mTOR signaling pathway." (PMID 33354489, 2020).